ALB (albumin)
Diseases named in the same sentence as ALB in open-access papers (continued):
Sharing a sentence is not in itself a finding about the gene and the disease.
malnutrition (continued). "Therefore, the association between serum TGF-β1 levels and hs-CRP may suggest the degree of vascular inflammation, while correlation with low serum albumin may suggest a state of malnutrition which is very common in CKD patients." (PMID 29977619, 2018). "In simple logistic regression, the consumption of one or more portions of fruit per day was significantly negatively associated with low serum albumin, while no other significant relationships were found between fruit and vegetables consumption and malnutrition or inflammation." (PMID 29324682, 2018). "The prevalence of malnutrition was approximately 18.7% using the Mini-Nutritional Assessment (MNA) (large or short form) as a diagnostic tool, but the prevalence was greater (45.7%) if different criteria were used (such as Body Mass Index (BMI), weight loss, or albumin concentration)." (PMID 29710860, 2018). "Given that malnutrition contributes to inadequate and incomplete wound healing, it could also lead to more devastating outcomes; parameters such as serum albumin and TLC are easily obtained, stable, inexpensive and established biochemical markers of nutritional status." (PMID 28093079, 2017). "Furthermore, serum albumin level has been regarded as a crucial parameter of malnutrition." (PMID 28978171, 2017). "Therefore, it seemed reasonable to use the combination of plasma fibrinogen and serum albumin for predicting survival of patients, and it could be more convincible because of the integration of hemostatic factors, malnutrition and SIR." (PMID 28978171, 2017). "The estimated BMI (p < 0.001) and concentrations of albumin (p < 0.001), hemoglobin (p < 0.001), total cholesterol (p < 0.001), prealbumin (p < 0.001) and total protein (p < 0.05) among subjects at high malnutrition risk by MNA were significantly lower than those without a risk." (PMID 28771192, 2017). "Furthermore, the lower ALB and malnutrition may weaken the ability of patients to confront stress and anticancer therapy, hence deteriorating the life quality and survival." (PMID 29069861, 2017). "However, in later stages, albumin synthesis is suppressed by inflammation and malnutrition." (PMID 29113384, 2017). "Secondly, a low ALB level may reflect malnutrition among cancer patients." (PMID 28654895, 2017). "Pre-albumin and transferrin are impacted by malnutrition and hepatic damage similarly, but respond faster and, therefore, could also be used as early indications of malnutrition." (PMID 29027963, 2017). "However, there is some contrary evidence that measuring albumin levels may be a useful tool for diagnosing malnutrition, especially in cardiac transplant and orthopedic patients." (PMID 27174435, 2016). "The serum albumin levels between patients with higher and middle to lower tertiles of NT-proBNP were similar, although the patients in the higher tertile of NT-proBNP showed a high prevalence of malnutrition compared with the patients in the middle to lower tertiles of NT-proBNP." (PMID 27870908, 2016). "Therefore, we hypothesized that the combination of D-dimer and albumin, which reflects malnutrition and poor survival in cancer patients, may provide a simple and objective prognostic scoring system for ESCC patients." (PMID 26754834, 2016). "Combined estimations of weight loss, serum measurements of CRP,albumin, urea, creatinine and alkaline phosphatase, preferably combined with othermethods using scores such as ECOG-PS, GPS and PG-SGA, were associated with relevantclinical outcomes such as malnutrition, survival and mortality." (PMID 26270855, 2015). "Indeed, low albumin could represent a marker of poor conditional status (i.e. cachexia, malnutrition, wasting syndrome, cirrhosis, nephritic syndrome)." (PMID 25899507, 2015). "Malnutrition may not be the only cause of low serum albumin in this patient population because many illnesses can alter serum albumin values." (PMID 26339558, 2015).
malnutrition (continued). "Serum albumin on admission was lower in nonsurvivors as well, which could indicate malnutrition, another predisposing factor for immunosuppression." (PMID 25210515, 2014). "Moreover, SOFA score does not include parameters of infection or malnutrition, diagnostic accuracy for post-ICU mortality was improved when combining SOFA score with serum PCT level (an indicator of infection) and serum albumin level (an indicator of malnutrition)." (PMID 25460569, 2014). "Blood indicators of malnutrition included the following routine blood chemistry investigations: Red Blood Cell Count, Hemoglobin, hematocrit, Mean Corpuscolar Volume, Mean Corpuscolar Hemoglobin, Mean Corpuscolar Hemoglobin Concentration, serum Iron, Transferrin, Albumin; Calcium, Phosphorus." (PMID 25000975, 2014). "As both inflammation and inadequate nutritional intake can decrease the level of serum albumin, much of the previously reported relationship between serum albumin, malnutrition, and mortality in patients undergoing HD may be due to an inflammatory process rather than poor nutritional intake." (PMID 24058552, 2013). "Albumin levels are influenced by many clinical manifestations other than nutritional status, which may limit the utility of using serum albumin as a specific marker of malnutrition." (PMID 22532840, 2012). "However, some studies indicated that albumin, as a marker of malnutrition, and not CRP, was associated with mortality in dialysis patients." (PMID 23300770, 2012). "However, it has not been well elucidated how dietary protein intakes are associated with serum albumin levels in general populations without extreme malnutrition." (PMID 20351474, 2010). "Albumin could potentially be used as an indicator of malnutrition and impaired hepatic function." (PMID 23675150, 2009). "However, we believed that this could be due to a "reverse" association, as progression of renal failure could result in decreased protein intake, malnutrition, and a decrease in serum albumin level." (PMID 15985177, 2005). "MELD-Albumin innovatively substitutes serum albumin for INR, considering that hypoalbuminemia is a significant marker of liver dysfunction, malnutrition, and acute-phase responses." (PMID 41602325, 2026). "In our study, albumin levels were significantly lower in patients with low HALP scores, underscoring the relationship between malnutrition, systemic inflammation, and early complications." (PMID 41594252, 2026). "The predictive value of this readily available biomarker is especially relevant in the geriatric setting, whereas systemic inflammation and malnutrition, two key components captured by CRP and albumin, frequently coexist and contribute to adverse outcomes." (PMID 40573094, 2025). "In the context of the biochemical milieu, frail patients exhibited lower serum albumin and GFR levels, alongside higher C-reactive protein (CRP) levels, indicating a state of chronic inflammation and malnutrition." (PMID 40283583, 2025). "Decreased serum albumin levels and an increased RDW have been related to inflammation, oxidative stress, and malnutrition." (PMID 41149135, 2025). "Albumin (ALB), an essential plasma protein, helps maintain osmotic pressure and transport nutrients, with decreased levels indicative of malnutrition or liver dysfunction." (PMID 40013138, 2025). "The MUST also stratified cancer type by level of malnutrition: UGI (27% by MUST score and 18% by albumin levels) and PAN (29% by MUST score and 22% by albumin) were significantly malnourished (p < 0.001)." (PMID 40458822, 2025). "The prediction efficiency of CNI was compared with other malnutrition indicators, such as Hb, TLC, ALB, BMI, UBW%, PNI, and NRI." (PMID 39508747, 2025). "Validated clinical tools include the Subjective Global Assessment (SGA) and the Malnutrition–Inflammation Score (MIS), which incorporates biochemical parameters such as serum albumin and total iron-binding capacity." (PMID 41228549, 2025).
malnutrition (continued). "The nomogram model incorporating RBC, ALB and NLR demonstrated robust predictive performance, particularly valuable for patients with malnutrition or pronounced inflammatory status." (PMID 40601767, 2025). "In the subsequent beta regression analysis, malnutrition remained a significant and independent predictor of increased relative IOH proportion after adjusting for age, sex, albumin, CRP, surgical approach, baseline MAP, and intraoperative factors." (PMID 41257946, 2025). "Although low albumin levels are generally associated with malnutrition, we hypothesize that the observed decrease in albumin may be a consequence of negative acute-phase reactant status, as indicated by elevated C-reactive protein (CRP) levels in the malnourished group." (PMID 40507738, 2025). "The serum creatinine/albumin ratio (CAR), a marker of renal dysfunction and malnutrition, has shown prognostic value in other critical illnesses but remains underexplored in HF patients." (PMID 40703630, 2025). "Low level of serum albumin (hypoalbuminemia) is a predictor of mortality in patients with ESRD and is connected to several factors including malnutrition, inflammation, and cardiac disease." (PMID 39780072, 2025). "The low albumin levels in the high CAR group can be explained by malabsorption and following malnutrition due to intestinal wall congestion." (PMID 40208300, 2025). "Based on the PNI value, which evaluates both inflammatory and nutritional statuses through ALB and CRP levels, it was established that 65% of T2DM patients demonstrated mild malnutrition." (PMID 40284203, 2025). "A statistically significant correlation was found between malnutrition (GLIM) and s-albumin (R = 0.2; p < 0.05) and hsCRP (R = 0.23; p < 0.05)." (PMID 40427596, 2025). "In summary, ALI, through the combined influence of BMI, albumin, and NLR, reflects malnutrition, chronic inflammation, and immune dysregulation in asthma patients, which in turn impacts both all-cause and CVD mortality." (PMID 39980677, 2025). "In advanced CKM syndrome participants, low ALB and high NLR often coexist, representing severe malnutrition and significant inflammatory responses." (PMID 40740647, 2025). "Based on the results of multivariate Cox regression analysis, the following predictors were identified for post-hepatectomy OS in patients with HCC: serum albumin, alpha-fetoprotein (AFP), maximum tumor diameter, tumor number, and GLIM malnutrition grade." (PMID 40642170, 2025). "Notably, the patient’s long-term vegetarian diet and potential malnutrition(Hemoglobin: 59.00 g/L; Prealbumin: 15.3 mg/dL; Albumin: 34.7 g/L) may have contributed to immune compromise, which is consistent with the growing evidence linking immune dysregulation to the development of MPMNs." (PMID 41584613, 2025). "Significantly lower albumin (p = 0.011) and lower MNA score (p = 0.001), indicating malnutrition, were observed in the group of CKD patients." (PMID 40566551, 2025). "The NPS is evaluated based on serum albumin, total cholesterol (TC) levels, NLR, and LMR and reflects inflammation, malnutrition, and immunosuppression." (PMID 39631788, 2025). "Malnutrition, identified through the use of SGA and serum albumin, has been correlated with the results of a qualitative examination of urinary protein in a study in China on 426 CKD patients." (PMID 40566551, 2025). "The RDW to albumin ratio (RAR) is a newly derived marker that is considered to be an indicator of inflammation and malnutrition." (PMID 40168268, 2025). "ROC analyses were performed to compare the prognostic value of CNI and other malnutrition indicators, such as Hb, TLC, ALB, BMI, UBW%, PNI, and NRI." (PMID 39508747, 2025). "The most used screening tools were the Malnutrition Screening Tool (MST; n = 32, 68%), the Malnutrition Screening Tool for Cancer (MSTC; n = 6, 13%), and/or biochemical measures (e.g. albumin; n = 6, 13%)." (PMID 40690045, 2025).
malnutrition (continued). "Similarly, patients at risk of malnutrition by CONUT were older and demonstrated higher systolic blood pressure, but lower BMI, lymphocyte count, total cholesterol, triglycerides, low-density lipoprotein, high-density lipoprotein, albumin, and estimated glomerular filtration rate." (PMID 40606134, 2025). "In contrast, nutritional status indicators were poorer in active IBD: serum albumin was significantly lower and the PNI was depressed, consistent with malnutrition and systemic inflammation." (PMID 41228452, 2025). "The combination of several instruments for assessing malnutrition, such as the GLIM criteria, albumin, HGS and low muscle radiodensity, resulted in a model with high prognostic power for mortality." (PMID 41019563, 2025). "Biochemical markers like serum albumin were not included alongside these anthropometric measures and body composition tools, though they could have offered a more comprehensive evaluation of malnutrition risk." (PMID 39683394, 2024). "IPF patients usually experience both pulmonary and systemic inflammatory responses, along with a state of malnutrition, which contribute to an increase in BUN levels and a decline in albumin." (PMID 39835108, 2024). "Cancer-related chronic inflammation and malnutrition typically lead to a decrease in AGR, primarily by reducing albumin levels and increasing globulin levels." (PMID 39170737, 2024). "Based on the GPS value, which reflects both the inflammatory and nutritional status using ALB and CRP levels, we found that 39% of T2DM patients had moderate-to-severe malnutrition status." (PMID 39682569, 2024). "CRP is a sensitive indication that can be used to discriminate between low- and high-level inflammation.The liver also produces albumin (ALB), which is frequently used as a marker of liver function and malnutrition." (PMID 38384810, 2024). "Patients diagnosed with malnutrition using the GLIM criteria, with SMI-BIA as the phenotypic criterion, exhibited significantly lower levels of albumin, prealbumin, SMI-L3, SMI-CT, SMI-BIA, and SMG compared to well-nourished patients." (PMID 39275350, 2024). "Malnutrition is a common complication in patients with CKD, which is characterized by lower serum albumin levels and decreased BMI." (PMID 39430784, 2024). "There were significant differences among the three groups in age, sex, BMI, SMI, sarcopenia, GNRI, malnutrition (GNRI < 92), hemoglobin, serum albumin, low serum albumin (≤ 3.5 g/dl), and predictive operative mortality calculated by JapanSCORE." (PMID 38436719, 2024). "For malnutrition, assessed using the 7-Point SGA, in ROC analysis albumin (area under the curve (AUC) 0.67 was the best single biomarker identified." (PMID 39125361, 2024). "Two studies have relied on specific nutritional markers like vitamin and albumin levels or utilized scales such as the mini nutritional assessment (MNA) and its short form (MNA-SF) to investigate the link between malnutrition and cognitive function." (PMID 39206308, 2024). "In this study, the ALB content in most elderly T2DM patients complicated with CI was lower than the normal range, indicating that malnutrition is common in elderly T2DM patients complicated with CI." (PMID 39148703, 2024). "Frail patients were found to be older and have lower albumin levels; however, this should not be regarded as a potential source of confounding bias, but rather an accompanying characteristic of frail patients; they are usually older and at risk of malnutrition." (PMID 38856830, 2024). "GLIM, created by four societies, is the first international malnutrition standard including inflammation, and it provides a more comprehensive assessment than the GPS, which uses only albumin and CRP." (PMID 39734937, 2024). "The patients who passed away in our study exhibited reduced levels of albumin and intracellular body water by BIA in multivariate COX regression, in relation to malnutrition stage." (PMID 39203824, 2024).
malnutrition (continued). "Significant predictive factors for malnutrition included age, body mass index, Eastern Cooperative Oncology Group (ECOG) performance status score, metastatic disease, albumin levels <3.0 g/dL, fatigue, and changes in stool/bowel habits." (PMID 39234292, 2024). "The patients with low LDL levels seemed to have lower phosphate and albumin levels compared with the other quartiles; therefore, having low LDL levels appears to be a marker of malnutrition and inflammation." (PMID 37784041, 2023). "In the female participants, those with low iron tended toward DM and malnutrition–inflammation, followed by higher MIS, higher UPCR, lower Hb, lower albumin, elevated WBC, elevated CRP, and elevated HbA1c in comparison with those with normal iron." (PMID 36983703, 2023). "Rats fed with RC, CTs, and TPTs showed lower serum albumin values, whereas the OHT diet was close to the lower limit of mild malnutrition (2.73 g/dL)." (PMID 37761036, 2023). "Nevertheless, no scientific study has shown a superiority in the link with screening for frailty and the measurement of malnutrition by the MNA scale compared to other assessment measures, such as the BMI scale and albumin level." (PMID 36976311, 2023). "Zinc, selenium, serum protein and albumin levels measured at study entry and over 48 weeks were compared between children aged 6 to < 36 months who were living with HIV and had SAM or mild malnutrition-normal nutrition." (PMID 37919816, 2023). "Blood albumin levels and BMI, which are sensitive indicators of PCM, were used to measure malnutrition." (PMID 37606393, 2023). "Therefore, low postoperative 4-week serum LDL-c levels may indicate malnutrition in patients, and the relatively low postoperative 4 weeks serum albumin level further confirmed the relatively poor nutritional status in the low LDL-c group, supporting our hypothesis." (PMID 37391827, 2023). "Albumin (ALB) is a typical repetitiveness of nutritional status that is synthesized by the liver and suppressed by malnutrition and systemic inflammation." (PMID 37996660, 2023). "Parameters related to nutritional health screening (serum albumin, BMI, MIS-malnutrition inflammation assessment, and dietary intakes) were carried out in 37.6%, 23.5%, 2%, and 2% of the DFs, respectively, only if recommended by physicians." (PMID 37733829, 2023). "These include albumin, BMI, MNA-SF, and the Global Leadership Initiative on Malnutrition (GLIM) criteria." (PMID 37324617, 2023). "In our study, four studies measured malnutrition using the MNA-SF, NRS-2002 in 2 studies, and MNA or albumin in 1 study." (PMID 37884977, 2023). "The malnutrition status was assessed using SGA, and clinical parameters including albumin and total leukocyte count (TLC)." (PMID 36694739, 2023). "Specific biomarkers reflecting pathophysiological pathways including specific proteins (e.g., albumin, prealbumin) and endocrine markers (e.g. thyroid hormones) may play a particularly important role here due to their involvement in the pathophysilogy of malnutrition." (PMID 37968689, 2023). "Malnutrition rates were assessed using different malnutrition criteria before CCRT: PG-SGA-defined severe malnourished status (20.5%), BMI <18.5 kg/m2 (22.7%), albumin levels <3.5 g/dL (11.4%), and TLC <1.5 × 103 cells/mm3 (31.8%)." (PMID 35804884, 2022). "Pretreatment malnutrition rates were assessed using different malnutrition criteria: PG-SGA-defined malnourished status (98.0%), BWL > 5.0% (26.0%), BMI < 18.5 kg/m2 (18.0%), albumin < 3.5 g/dL (18.0%), and TLC < 1.5 × 103 cells/mm3 (34.0%)." (PMID 36079741, 2022). "Malnutrition is the most frequent complication in patients with ALD, including a low lean body mass, low plasma albumin, etc.." (PMID 36290494, 2022).